IFNG (interferon gamma)
Diseases named in the same sentence as IFNG in open-access papers (continued):
Sharing a sentence is not in itself a finding about the gene and the disease.
Sepsis (526 papers, 2007 to 2026). Sepsis is defined as life-threatening organ dysfunction caused by a dysregulated host response to infection. "The present literature overview reveals a central role of IFNγ in sepsis pathology and is supported by association of nucleotide polymorphisms in the IFNγ gene with endotypes of sepsis." (PMID 40762872, 2025). "It was finally proved that IFNγ promoted the Warburg effect through the PI3K/Akt/mTOR pathway to reverse the immunosuppression caused by sepsis." (PMID 37434129, 2023). "The results showed that IFNγ inhibit the apoptosis caused by sepsis and that 2-DG aggravated this effect." (PMID 37434129, 2023). "Immature neutrophils, characterised by lower or absent CD10, are immunostimulatory by promoting T-cell proliferation, survival and IFNγ production and have been associated with poor prognosis in sepsis." (PMID 35386227, 2022). "During septic shock, M1 macrophages polarized by IFNγ or LPS participate in inflammatory immune responses, whereas M2 macrophages play essential roles in repairing tissue injury caused by sepsis-induced inflammation." (PMID 33809795, 2021). "Endothelial permeability increased with LPS and IFNγ which indicates that the experimental system reproduces to some extent the clinical effects of sepsis, namely vascular leakage and loss of glycocalyx." (PMID 29717213, 2018). "For our study we have used human macrophages activated with interferon gamma, because we believe that this more accurately reflects the state of macrophages during sepsis caused by B. pseudomallei." (PMID 27484700, 2016). "IL-12+DC cells induced pathogenic IFNγ+Th1 and IL-17+Th17 cells in peripheral blood and lymph nodes, whereas IL-12, secreted by DC cells in the peritoneal cavity, protected against sepsis." (PMID 23936099, 2013). "Acute sepsis is characterized by the loss of circulating innate and adaptive immune cells and impaired secretion of IFNγ." (PMID 22742734, 2012). "Both, high- and low-expressing IFNγ phenotypes of sepsis, might be related to nucleotide polymorphisms of the human IFNγ gene." (PMID 40762872, 2025). "To test whether acute and systemic inflammation in mice might affect extracellular pT73-Rab10 to total Rab10 ratios, we introduced a polymicrobial sepsis challenge to outbred CD-1 mice that caused large increases in serum concentrations of IFNγ and TNF." (PMID 38862989, 2024). "However, high IFNγ levels in early sepsis are associated with secondary candida infection, suggesting its role as an immunosuppressive mediator." (PMID 38057824, 2023). "Recombinant IFNγ treatment was also able to partially restore immune metabolic defects associated with immune paralysis in humans after sepsis, further suggesting that IFNγ therapy after sepsis may benefit a multitude of cellular immune functions." (PMID 29163354, 2017). "In addition, these IL-12+DC cells induced pathogenic IFNγ+Th1 and IL-17+Th17 cells in peripheral blood and lymph nodes, whereas IL-12, secreted by DC cells in the peritoneal cavity, elucidated its important properties for protecting against sepsis." (PMID 23936099, 2013). "Both, excessive pro-inflammatory responses with high IFNγ and downstream mediators, such as chemokines (CXCL9), as well as immunosuppression with low IFNγ levels are associated with unfavorable outcomes in sepsis." (PMID 40762872, 2025). "In this scoping review, we explore the correlation of IFNγ levels to sepsis endotypes and put these into perspective of the knowledge on chronic states of altered IFNγ signaling." (PMID 40762872, 2025). "The differences in the systemic basal levels of β-glucan in sepsis patients as well as the pulmonary levels of IFNγ can be major factors in determining the hyperresponsiveness in sepsis patients and can be potentially targeted for therapy." (PMID 40624927, 2025).
Sepsis (continued). "Downstream induction of CXCL9 (but not of CXCL10 and 11) occurring in a subset of patients with high IFNγ levels has been shown to correlate with the hyper-inflammatory phenotype of sepsis." (PMID 40762872, 2025). "This review summarizes current knowledge on the IFNγ response to infection and attempts to relate the IFNγ response to endophenotypes of sepsis in the human host." (PMID 40762872, 2025). "SLC25A33 expression was significantly elevated in CD14+ monocytes derived from patients with sepsis and LPS/interferon-gamma (IFN-γ)-stimulated peritoneal macrophages (PMs)." (PMID 40384854, 2025). "Due to the key importance of highly contrasting phenotypes and the dynamics of patient responses in sepsis pathogenesis, reliable diagnostics are essential prerequisites for assessing IFNγ-targeted treatment approaches in sepsis patients." (PMID 40762872, 2025). "In contrast to the discussed efforts to restore adaptive and innate immunity in immunosuppressed sepsis patients, evidence for the benefit of IFNγ antibody therapy for the hyper-inflammatory phenotype is still missing." (PMID 40762872, 2025). "Markers of an IFNγ response were higher in sepsis than in healthy patients, including IL-18 (p=0.02) which increases IFNγ production and MIG (p<0.0001), an IFNγ inducible chemockine." (PMID 39935482, 2025). "Intravenous infection also resulted in significantly elevated levels of IFNγ-expressing cells across all lymphocyte populations, which again correlated strongly with the sepsis score." (PMID 40178612, 2025). "Beyond these two immune states, recent research has identified a third independent endotype driven by interferon-gamma (IFNγ), termed IDS (IFNγ-driven sepsis)." (PMID 40265185, 2025). "Regarding clinical evaluation of manipulation of this signaling pathway is currently focused on recombinant IFNγ to treat sepsis-induced immunosuppression." (PMID 40762872, 2025). "In a murine model, clearance of secondary Pseudomonas infection is hampered after sepsis induction by cecal ligation and puncture due to impaired IFNγ production from NK cells." (PMID 38426112, 2024). "For instance, immunostimulatory agents such as interferon-gamma [IFNγ] and granulocyte–macrophage colony-stimulating factor (GM-CSF) have been the most widely researched in sepsis." (PMID 38247605, 2024). "Strikingly, we find that the pairwise effects of tumor necrosis factor plus interleukin (IL)-18, interferon-gamma or IL-1β suffice to mirror the impact of sepsis across tissues." (PMID 38191855, 2024). "Since, lymphopenia is a critical component of sepsis and critical illness, we normalized IFNg production to cell count, thus distinguishing between quantitative and qualitative lymphocyte defects." (PMID 39712015, 2024). "In sepsis, the hypermethylation of genes involved in immune activation, such as interferon-gamma (IFN-γ) and tumor necrosis factor-alpha (TNF-α), contributes to immune paralysis by silencing pro-inflammatory pathways essential for pathogen clearance." (PMID 39594987, 2024). "IFNγ is a clinically proven sepsis immunotherapy whose effect is inseparable from metabolic regulation." (PMID 37434129, 2023). "Explain the immunostimulation therapy mechanism of IFNγ, find new targets for immunostimulation therapy for sepsis, and enrich the individualized treatment of sepsis." (PMID 37434129, 2023). "This study elucidates the potential mechanism of the immunotherapeutic effect of IFNγ in sepsis, providing a new target for the treatment of sepsis." (PMID 37434129, 2023). "Adjuvant immunotherapy with IFNγ was well-tolerated, improving immune function in sepsis-induced immunosuppression." (PMID 37434129, 2023). "Our experiments comprehensively demonstrated the immune stimulation mechanism of IFNγ from two parts in vivo and in vitro, and found that sepsis immunosuppression can be treated by modulating the Warburg effect." (PMID 37434129, 2023).
Sepsis (continued). "Interferon γ (IFNγ) is a potential therapy for immunosuppression of sepsis, promoting glycolysis to restore metabolic defects in monocytes, but the mechanism of treatment is unclear." (PMID 37434129, 2023). "Additional hallmarks of immune suppression in sepsis are impaired T lymphocyte interferon gamma (IFN-γ) production and decreased monocyte HLA-DR expression." (PMID 36906875, 2023). "According to our image analysis, the expression of autophagosomes in the LPS-induced sepsis group increased and that IFNγ treatment reduced the expression of autophagosomes." (PMID 37434129, 2023). "The high PANoptosis group, associated with interferon alpha and gamma signaling, neutrophil degranulation, and type II interferon signaling IFNG, highlights the significance of immune modulation in sepsis pathology." (PMID 38239341, 2023). "While only ELISpot revealed a relationship between LPS-induced TNF production over time, both assays revealed decreases in total and lymphocyte-adjusted IFNγ concentrations over the first 2 weeks following sepsis/critical illness." (PMID 37831231, 2023). "The role of IFNγ in the immunosuppressive therapy of sepsis has been validated in clinical practice." (PMID 37434129, 2023). "An mRCT on IFNγ for sepsis-related immune paralysis ended early due to slow enrollment (< 30% CD14 monocytes with HLA-DR)." (PMID 38057824, 2023). "Contrary, monocytic HLA-DR-guided immunostimulatory therapy with CSF2 (Granulocyte–macrophage colony-stimulating factor) or IFNγ, have shown promising results in patients with severe sepsis." (PMID 36829233, 2023). "In order to clarify the role of IFNγ in the apoptosis of immune cells during sepsis, apoptosis was quantitatively detected via the TUNEL assay." (PMID 37434129, 2023). "In order to explore the effects of sepsis, IFNγ, 2-DG, and LY294002 on metabolism, commercially available kits were used to detect glucose uptake and the content of extracellular lactate, intracellular ATP, and metabolism-related proteins." (PMID 37434129, 2023). "Studies have shown that IFNγ treatment can promote glycolysis to restore the function of monocytes in the peripheral blood of patients with sepsis." (PMID 37434129, 2023). "IFNγ also reduces CD4 + T cell inhibitory receptor expression and systemic inflammation in septic mice; however, the mechanism by which IFNγ exerts immune regulation in sepsis is unclear." (PMID 37434129, 2023). "Interferon-gamma (IFN-γ) and IL-10 were ascribed prognostic and predictive value for sepsis outcome and therapy, as a low IFN-γ/IL-10 ratio was predictive for positive hydrocortisone therapy response in septic shock patients." (PMID 35732880, 2022). "As expected, such changes ultimately led to proinflammatory cytokine production during late-stage sepsis (IL-1β, IL-6, IFNγ, TNFα)." (PMID 35349828, 2022). "Inflammatory mediators such as the pro-inflammatory cytokines IL-1β, TNFα, and IFNγ, secreted during sepsis, have been shown to induce chemerin expression in adipocytes as well as other cells." (PMID 35204801, 2022). "The statistical analysis indicated that, compared with those in the sham group, IL-1β, TNFα, IL-6, and IFNγ levels in the Sepsis group were upregulated, while SOD and GSH-PX levels were downregulated." (PMID 34489703, 2021). "Whereas sepsis patients exhibiting low bacterial load predominantly release the cytokine, interferon-gamma (IFNγ), the inflammation-inhibiting cytokine, interleukin-10 (IL-10), prevails in bacteremic patients with a high bacterial load." (PMID 34964952, 2021). "In fact, a fundamental role of type 1 and type 2 interferon signaling in modulating response to endotoxin and endotoxin tolerance has been reported, including a clinical trial using IFNg to mitigate immune paralysis in sepsis." (PMID 34867954, 2021).
Sepsis (continued). "In fact, IFNγ, whose receptor signals through JAK2, is believed to partially rescue the endotoxin tolerance phenotype in human monocytes, and IFNγ is sometimes used in sepsis treatment to improve immune host defense, perhaps activating JAK2 more intensively." (PMID 34867954, 2021). "We then applied the assay to assess the relative distribution of the isomers in different blood compartments, the effect of stimulation with LPS/IFNγ (mimicking a sepsis-like inflammation), and differences in concentration among various mouse organs." (PMID 33925995, 2021). "T cells harvested from the spleen of patients who died of sepsis have only a low capacity to produce IFNγ and TNF, suggesting a state of T-cell exhaustion." (PMID 33679715, 2020). "Sepsis scores were thus found to be in strong linear correlation with the concentrations of IL-6, IFNγ, and TNFα and again, higher sepsis scores in mice with pre-existing CIA correlated with elevated levels of these cytokines." (PMID 33117382, 2020). "To further confirm that MAIT cell effector function is impaired during experimental sepsis, we evaluated IFNγ, TNFα, IL-17a, GM-CSF, and IL-10 protein expression in MAIT cells of lung tissue using flow cytometry." (PMID 33164745, 2020). "IFNγ has been shown to improve phagocytic capacity and HLA-DR expression on monocytes in human sepsis and related to earlier recovery from sepsis." (PMID 33679715, 2020). "Guided by clinical and immunological monitoring, adjunctive immunotherapy with IFNγ appears well-tolerated in our cases and improves immune host defense in sepsis induced immuno suppression." (PMID 31690258, 2019). "At 72 HPI, sepsis appeared to have progressed, with an increase in serum IFNγ, IL1β, IL10, and TNFα." (PMID 31121001, 2019). "This study went on to generate in vivo data which revealed that in a mouse model of sepsis, mice that transgenically overexpress NeST exhibit greater expression of IFNγ and an increase in the proportion of H3K4me3 marks at the IFNγ locus." (PMID 31336952, 2019). "In order to evaluate the occurrence of sepsis-induced T-cell functional alterations in this cohort, we measured intracellular IL-2, TNFα, and IFNγ productions after ex vivo activation of T lymphocytes from patients and HVs." (PMID 30995946, 2019). "Several immunotherapies have undergone clinical trials in sepsis with promising results, including recombinant interleukin-7 (IL-7), interferon-gamma (IFN-γ), Fms-like tyrosine kinase 3 ligand, and chimeric antigen receptor T cell (CAR-T)." (PMID 31187301, 2019). "A similar pattern of decreased TNFα, IL-6, IFNγ, and IL-10 was also observed in a post-mortem study of stimulated splenocytes from patients who died of sepsis." (PMID 30555806, 2018). "Granulocyte-macrophage colony stimulating factor (GM-CSF) and interferon-gamma (IFNγ) are the most extensively investigated immunostimulatory agents in sepsis." (PMID 30233566, 2018). "To assess the function of the antigen-receptor following SIRT1 treatment during sepsis immune tolerance, we measured IFNγ production from total T cell antigen-receptor-stimulated T cells (including CD4+ and CD8+)." (PMID 30069485, 2018). "Impaired NK cell function with reduced IFNγ secretion and cytotoxicity has been reported in patients with sepsis, while others have found normal NK cytotoxic function in severe sepsis." (PMID 30459764, 2018). "Heparan sulphate proteoglycan 2, a glycocalyx component found to be increased in the urine of sepsis patients experiencing capillary leakage, was also lost during LPS and IFNγ stimulation of HUVECs55,56." (PMID 29717213, 2018). "During sepsis, the levels of IFNγ, IL-6, IL-10, and IL-4 were significantly elevated in the moderate preterm group only." (PMID 30555806, 2018). "Natural killer (NK) cells play a crucial role in the pathophysiology of sepsis, leading to exaggerated inflammation due their rapid response and production of pro-inflammatory cytokines such as interferon gamma (IFN-γ)." (PMID 28287491, 2017).
Sepsis (continued). "Patients with severe sepsis treated with recombinant IFNγ demonstrate reversal of sepsis-induced monocytic dysfunction, as well as having better overall survival." (PMID 29163354, 2017). "In order to study the underlying mechanisms, we then tested the excessive release of Angpt-2 from ECs upon stimulation with various sepsis mediators (i.e. IL-1ß, TNFα, LPS, IFNγ)." (PMID 28276491, 2017). "Similar to our current findings, pre-treatment with I-BET-762 has previously been shown to reduce serum IFNγ levels and protect mice in a lethal sepsis induced by LPS." (PMID 27657907, 2016). "As the major interferon-gamma (IFN-γ) producers in the early stages, NK cells contribute to the promotion of inflammation in bacterial infection and sepsis." (PMID 27548133, 2016). "Subsequent elevation of the genes encoding the inflammatory chemokines such as CCL16, CCL25 and CXCL6, and cytokines such as IL-2, IL-8 and IFNG in concert with delayed activation of the coagulation system are the typical signatures of sepsis." (PMID 27003632, 2016). "We went further and analyzed the bacterial infection responsive genes derived from our M(IFNγ + LPS, TNFα) signature and applied in predicting sepsis outcome." (PMID 26302899, 2015). "P14 T-cells from control and all SIRS/sepsis groups reacted equally well to the in vivo GP33 antigenic challenge in terms of IFNγ production." (PMID 25541945, 2014). "Specifically, sepsis survivors had increased expression of genes involved in the immune response including response to interferon-gamma, the defense response, and the innate immune response." (PMID 25538794, 2014). "Sepsis is caused by a systemic response to infection, which is characterized by elevated levels of proinflammatory cytokines such as TNF-α, IL-1β, IFNγ and IL-6 in the circulation or in inflamed tissues." (PMID 25269519, 2014). "When patients with infection and patients with severe sepsis on ICU admission were compared, IL2, IL7, IL23, IFNγ, and TNFα gene expression was lower in patients with sepsis, while IL-27 gene expression was similar in these two groups." (PMID 23935244, 2013). "CLP-induced sepsis significantly up-regulated IFNγ+Th1 and IL-17+Th17 cells in DC-undepleted mice, compared with the sham control." (PMID 23936099, 2013). "• Lymphocytes from patients with sepsis have impaired secretion of IFNγ when measured at both the onset of sepsis and again later in the course of the disease." (PMID 22742734, 2012). "The authors could model hepatic-immune dysfunction during sepsis by adding lipopolysaccharide (LPS) and interferon-gamma (IFN-γ)." (PMID 40604306, 2025). "Patients with purely pro-inflammatory sepsis may present with macrophage activation-like syndrome (MALS) or the interferon-gamma (IFNγ)-driven sepsis endotype (IDS)." (PMID 40007937, 2025). "In addition to these well-characterized effects of IFNγ, recent studies disclose a key role of the cytokine in sepsis and organ dysfunction." (PMID 40762872, 2025). "Consequently, intravenous infection was characterized by a strong correlation between IFNγ expression and the sepsis score for the mentioned cell types." (PMID 40178612, 2025). "In addition, during sepsis, the major interferon-gamma (IFN-γ)- producing natural killer (NK) cells encounter immoderate apoptosis after a reduced number is present in the circulation, thus increasing the risk of secondary infection." (PMID 39720718, 2024). "We analyzed whether the polymorphism was correlated with the cytokine expression of IL1β, IFNα2, IFNγ, TNF-α, IL-33, IL12p70, MCP-1, IL-6, IL-10, IL-17a, IL-18, or IL-23 to further investigate the effect of the polymorphism in sepsis patients." (PMID 38338680, 2024). "During sepsis, the innate immune system acts as the primary defense for the host, with immune cells like monocytes/macrophages becoming hyperactivated, releasing copious inflammatory cytokines, such as interleukin (IL)-1β, IL-6 and interferon-gamma (IFN-γ)." (PMID 39320524, 2024).